IL6 (interleukin 6)
Diseases named in the same sentence as IL6 in open-access papers (continued):
Sharing a sentence is not in itself a finding about the gene and the disease.
bacteremia (continued). "IL-6 is an early biomarker in bacteremia that is used to evaluate the inflammatory response." (PMID 33588861, 2021). "In summary, a high bacterial antigen load seems to be associated with the induction of IL-6 and TNF-α, and could cause an inflammatory cascade during bacteremia, potentially contributing to a detrimental outcome of invasive S. suis infection." (PMID 31947746, 2020). "We could detect an induction of IL-6 and the anti-inflammatory mediator IL-10 in serum of intravenously S. suis-infected piglets (after 13–19 hpi) that showed a pronounced bacteremia." (PMID 31947746, 2020). "Consistent with the literature, in this study, patients who died from SAB had significantly higher IL-6 and IL-10 levels during early-stage bacteremia, and patients who died within 7 days of SAB onset further displayed a significantly elevated IL-10/TNF-α ratio and TLR2 downregulation." (PMID 33256638, 2020). "The observed in vivo induction of IL-6 and IL-10 in bacteremic pigs raises the question of whether the induction of pro-inflammatory cytokines also has protective properties in bacteremia." (PMID 31947746, 2020). "As we observed an induction of IL-6 and IL-10 in piglets with pronounced bacteremia, we tested whether cytokine induction could be reproduced in a whole-blood assay upon addition of viable S. suis, as has been demonstrated previously." (PMID 31947746, 2020). "The aim of the study was to evaluate the effects of continuous hemofiltration on 28-day mortality and the levels of total bilirubin (TBIL), direct bilirubin (DBIL), total bile acids (TBA), lactate (Lac), ammonia, TNF-α and IL-6 in patients with bacterial sepsis complicated by liver dysfunction." (PMID 30098593, 2018). "In previous reports, particularly the pro-inflammatory cytokine IL-6 and the anti-inflammatory cytokine IL-10 have been positively correlated to different markers of severity such as mental confusion, hypotension, pleural effusion, and bacteremia." (PMID 26407163, 2015). "In both bacteremia and viremia, an isolated significant increase of IL-6 was observed." (PMID 26315105, 2015). "We also found that bacteremia was strongly and positively correlated with IL-6 concentrations." (PMID 25888135, 2015). "In another retrospective study, significant increases of IL-6, IL-8 and sIL-2R were observed during the analysis of febrile episodes before bacteremia caused by gram-negative bacteria." (PMID 26315105, 2015). "In addition we identified several modest genetic associations, especially between TLR5 SNP rs5744168 and UTI and between IL6 SNP rs1800795 and occurrence of bacteremia." (PMID 25807366, 2015). "Another marker is interleukin-6 (IL-6), which may be detectable in the early stages of infection and bacteremia." (PMID 25309126, 2014). "Blocking cytokines such as TNF- α, IL-6 and IL-1 did show benefit in patients with bacteremia." (PMID 21931850, 2011). "In this study we analyzed the significance of serum levels of the proinflammatory cytokines IL-6 and IL-8 as well as C-reactive protein as predictors for severe bacterial infection or bacterial sepsis in children with fever and neutropenia during cancer chemotherapy." (PMID 18321393, 2008). "IL-6 is secreted by monocytes andmacrophages in response to bacteremia." (PMID 18274637, 2007). "IL-6 ≥ 18.79 pg/mL indicated the presence of pulmonary bacterial infection in patients, and IL-6 ≥102.6 pg/mL may suggest pulmonary bacterial infection with bacteremia." (PMID 39559703, 2024). "Moreover, procalcitonin (p < 0.001) and IL-6 (p = 0.036) were higher in the bacterial sepsis group." (PMID 36982221, 2023). "Although serum IL-6 is a biomarker associated with the severity of bacterial sepsis, the IL-6 level could not differentiate between dengue in febrile and critical phases." (PMID 35782108, 2022).
bacteremia (continued). "In conclusion, 28-day mortality of patients with bacterial sepsis-associated liver dysfunction was significantly improved in the continuous hemofiltration group, which was related to the decreased serum levels of TBIL, DBIL, TBA, Lac, ammonia, TNF-α and IL-6 after 72 h treatment." (PMID 30098593, 2018). "In our study on ROC analysis IL-6 performed good, with AUC 0.87, which is quite close to results of Groselj-Grenc - AUC 0.776 for acute appendicitis diagnosis in children, and marginally different from results in Pavcnik-Arnol study - AUC 0.67 for prediction of bacterial sepsis in neonates." (PMID 20158885, 2010). "While more sensitive than CRP (29%), IL-6’s elevation in 57% of FUO episodes (37/65) and failure to detect 26% of bacteremia (9/34) precluded standalone use for antibiotic decisions." (PMID 40647525, 2025). "In the prediction of mortality, the combination of IL-6 and CRP reached 92% sensitivity in the presence of bacteremia but specificity was relatively low at 78%." (PMID 41011807, 2025). "Nonetheless, both vaccinated and unvaccinated SARS-CoV-2 patients exhibited markedly lower IL-6 and PCT levels compared to those with bacterial sepsis." (PMID 41472286, 2025). "Using a cutoff of >16.6 pg/mL, IL-6 achieved 92.8% sensitivity, outperforming CRP (73.1%) and procalcitonin (PCT; 33.8%) in bacteremia detection (p < 0.01)." (PMID 40647525, 2025). "Resistin expression was notably higher in patients with G- bacterial sepsis contrasted with G+ bacterial sepsis (P < 0.05) Furthermore, resistin levels were significantly correlated with PCT, IL-6, and PDL1 (P < 0.05)." (PMID 40568710, 2025). "Also, our study demonstrated that the presence of bacteremia in the initial blood sample taken from intensive care patients holds significant diagnostic and prognostic value even without waiting for species-level identification when combined with markers such as PCT, CRP, and IL-6." (PMID 41011807, 2025). "In bacteremia, IL-6 and IL-10 were more positive than PCT and CRP, and IL-6 and IL-10 were significantly more specific than PCT in the diagnosis of diagnostic G- bacteremia." (PMID 39559703, 2024). "The specificity of IL-6 and IL-10 was significantly higher than that of PCT in the diagnosis of G- bacteremia." (PMID 39559703, 2024). "In recent years, medical practitioners have explored more rapid biomarkers for diagnosing bacteremia, including procalcitonin (PCT), C-reactive protein (CRP), and interleukin-6 (IL-6)." (PMID 39885965, 2024). "Early response cytokines (i.e. first wave at initiation of bacteremia) included IFN-γ, IL-1β, IL-6, IL-18, IL-1ra, IL-10, IL-12 (p40), IL-17a and MCP-1, which all reached peak levels during bacteremia." (PMID 35925895, 2022). "The distribution of one SNP, rs1800795 in the gene IL6, was significantly different as the genotype CC is more common among UTI patients with bacteremia (p = 0.009)." (PMID 25807366, 2015). "Cytokines and chemokines, including IL-6, IL-10, IL-17A, and MIP-2 were induced systemically and in the lungs of rats with S. aureus bacteremia." (PMID 25978669, 2015). "In the bacterial sepsis-ARDS group, levels of IL-6, IL-8, IL-9, IL-15, IL-17, IP-10 and TNFα are also increased versus the control group." (PMID 21062445, 2010). "Subsequently, the bacteremia as well as cytokines from the periodontal lesion will stimulate the hepatocytes and leucocytes to produce CRP and IL-6." (PMID 20407653, 2009). "While IL-6 showed weak correlation with CRP during Days 1–2 of fever (r = 0.25, p = 0.02), serum amyloid A demonstrated superior sensitivity for bacteremia (100% vs. CRP’s 68%)—though the study cautioned against its standalone use due to false-positives in viral infections." (PMID 40647525, 2025). "Inflammatory markers, including IL-6 and PCT, were higher at ICU admission in bacterial sepsis." (PMID 41472286, 2025).
bacteremia (continued). "Despite IL-6’s superior sensitivity compared to CRP (74% vs. 29%), its elevation in 57% of FUO episodes and failure to detect 26% of bacteremia precluded standalone use for antibiotic decisions, underscoring the limitations of single biomarkers in neutropenic fever management." (PMID 40647525, 2025). "Also, IL-6, PCT and CRP combination demonstrated 90% sensitivity and 85% specificity for predicting mortality with bacteremia." (PMID 41011807, 2025). "Both maximum median IL-6 levels (2513 ng/L [626.00–24,245.00] vs. 188.00 ng/L [84.90–540.00]; p < 0.001) as well as PCT levels (17.80 μg/L [8.72–57.05] vs. 0.44 μg/L [0.22–2.05]; p < 0.001) were significantly higher in patients with bacterial sepsis." (PMID 41472286, 2025). "IL-6 showed no discriminative power for bacteremia and correlated weakly with CRP only on Days 1–2 (r = 0.25, p = 0.02)." (PMID 40647525, 2025). "It is significant that, unlike previous studies, we measured IL-6 and IL-10 concentrations serially throughout the bacteremia period." (PMID 38969796, 2024). "We found that IL-6 had a high specificity at a threshold set to detect 100% of Gram-negative sepsis and NEC cases but low predictive accuracy for Gram-positive cases, which were mostly due to CONS bacteremia." (PMID 38312920, 2024). "The discrepancy from our study suggests that measuring IL-6 with CRP and/or PCT may be useful to detect infection or bacteremia more quickly and correctly in diverse situations." (PMID 36555941, 2022). "Notably, in our study IL-6 levels were comparable between the two ARDS groups, while its receptor IL-6RA was higher in COVID-19 ARDS compared to bacterial sepsis-induced ARDS." (PMID 36121875, 2022). "However, there was a pattern in 75% of patients that was distinct from bacterial sepsis: TNF-alpha and IL-6 production by circulating monocytes were sustained; furthermore, there were high levels of CRP, d-dimer and AST/ALT." (PMID 36289881, 2022). "Regardless of the occurrence of bacteremia or fungemia, the CRP, PCT, and IL-6 levels showed significant differences on each day of hospitalization, and this discrepancy was larger in the absence of bacteremia." (PMID 36555941, 2022). "Despite no bacteremia in all groups (data not shown), serum IL-1β, IL-6, and TNF-α (but not IL-10) were increased in the infected mice from both bacterial strains." (PMID 35955437, 2022). "Among all groups, only mice with SE > CT biofilms demonstrated mortality with the highest serum pro-inflammatory cytokines (TNF-α and IL-6), organ injury (kidneys and livers), and fungemia, but not bacteremia." (PMID 34746032, 2021). "Our study revealed that the cytokines IL-2, IL-6 and IL-10 were significantly higher in candidemia patients than in bacteremia patients, which was not reported in previous studies." (PMID 34684298, 2021). "In contrast, no increase in IL-6 or IL-10 levels was detectable in the sera of three pigs, which were able to control bacteremia, as well as in the three uninfected control pigs." (PMID 31947746, 2020). "Longitudinal analyses by LMM revealed that TNF-α, IL-6, and IL-10 concentrations were significantly increased in SAB patients who died within 30 d post-bacteremia (with SAB patients who survived as reference) (p = 0.001, p = 0.002, and p < 0.001, respectively)." (PMID 33256638, 2020). "In our study, we found that IL-8 was a strong predictive marker for bacteremia, particularly for gram-negative bacteremia, as compared to IL-6 and CRP." (PMID 28148470, 2017). "They hypothesized that the neutralizing activity of anti-IL-6 autoantibodies may have resulted in a block of IL-6 signaling and therefore inhibiting the production of CRP, thus leading to severe bacterial sepsis." (PMID 31557985, 2016). "While IL-6 and IL-8 are good biomarkers for infection, we found that they cannot distinguish between patients with or without bacteremia." (PMID 25807366, 2015).
bacteremia (continued). "According to the binary logistic regression analysis, TNF-α, IL-1α, KC, G-CSF, IL-6, IL-12p70, IP-10, and MIP-1α are indicative for presence of S. aureus bacteremia in mice, while TNF-α, IL-1α, and KC were also potential biomarkers for fatal outcome of this infection." (PMID 23520553, 2013). "When episodes of bacteremia caused by Gram-positive and Gram-negative bacteria were compared, CRP and IL-6 blood level were found to be significantly higher in Gram-negative bacteremia." (PMID 20202204, 2010). "IL-6 and IL-8 levels were higher in patients with either bacteremia due to Gram-negative organisms or fungal infections than in patients with febrile episodes without an identifiable source." (PMID 18321393, 2008). "In the follow-up analysis of blood samples, we did not observe differences in bacteremia, plasmatic concentration of liver and kidney damage markers, and plasmatic IL-6 concentrations assessed in the first 6 h, indicating a similar initial inflammatory response across all mice." (PMID 40241761, 2025). "Bacterial sepsis induces systemic inflammation, which stimulates PCT production in almost all tissues released into the blood stream in response to bacterial endotoxins and inflammatory cytokines, such as tumor necrosis factor-alpha (TNF-α), interleukin-1-beta (IL-1β), and interleukin-6 (IL-6)." (PMID 39195007, 2024). "No steady decrease in CRP, PCT, and IL-6 levels was observed in the absence of bacteremia." (PMID 36555941, 2022). "However, we must prudently decide the antimicrobial treatment to avoid overuse of antibiotics, because a single increase in IL-6 does not directly indicate infection or bacteremia." (PMID 36555941, 2022). "Besides, the levels of IL-6, IL-8, and IL-10 in bacterial sepsis nonsurvivors and the levels of IL-6 and IL-10 in SARS-CoV-2 sepsis nonsurvivors were higher when compared with the corresponding survivors." (PMID 33329592, 2020). "IL-6 and IL-10 levels were significantly higher in non-survivors than in survivors on days 2–5 post-bacteremia (P = 0.010 and P = 0.021, respectively), and those dying within 7 d of SAB (n = 3) displayed significantly higher IL-10/TNF-α ratios than the survivors did (P = 0.007)." (PMID 33256638, 2020). "In addition, similar to the samples in our cohort, at inclusion IL-6 production in the Swedish patients was not significantly different between patients with or without bacteremia." (PMID 25807366, 2015). "We analyzed various proteins in urine of UTI patients and controls from a prospective cohort study and found that while IL-6, IL-8 and cathelicidin LL37 are different between UTI patients and controls, these proteins, as well as β-defensin 2, cannot be used as biomarkers for bacteremia." (PMID 25807366, 2015). "Compared to conventional infection markers such as IL-6, CRP, and WBC, NLR exhibits a high degree of sensitivity, specificity, and positive rate for bacteremia and is not affected by the type of transplanted organ or the patient’s sex." (PMID 40276743, 2025). "Unlike IL-6, CRP, and PCT, sNRP-1 showed stable elevated levels in the bacterial sepsis group throughout the 7-day observation period." (PMID 40733612, 2025). "Whilst IL-6, PCT, and presepsin levels were significantly higher in patients with bacteremia than in those without bacteremia." (PMID 37324133, 2023). "Subjects with detectable bacteremia had lower levels of HGF (p = 0.005), IL-15 (p = 0.002), IL-6 (p = 0.05), IP-10 (p = 0.008), MIG (p = 0.03) and MIP-1α (p = 0.03) compared to subjects without bacteremia." (PMID 28628613, 2017). "The production of the cytokines IL-6 and IL-8 was determined in urine samples from 44 UTI patients without bacteremia, 45 UTI patients with bacteremia and 46 controls." (PMID 25807366, 2015). "IL-6 was detected in 30 of all 89 (34%) UTI patients, in 12 of 44 (27%) without bacteremia and in 18 of 45 (40%) with bacteremia, and in none of the controls." (PMID 25807366, 2015).
bacteremia (continued). "IL-6, IL-8, and LL37 are different between controls and UTI patients, although these proteins do not distinguish between patients with and without bacteremia." (PMID 25807366, 2015). "Remarkably, increased levels of IL-6 and IL-8 are effective in determining whether or not pulmonary bacterial infectious NHL patients have bacteremia." (PMID 35463642, 2022). "An increase in IL-6 and IL-10, but not in IFN-γ or IL-17A, was observed in two of three piglets with pronounced bacteremia 16 to 20 h after infection, but not in piglets with controlled bacteremia." (PMID 31947746, 2020). "Genotypes of IL6 variation in UTI patients with and without bacteremia." (PMID 25807366, 2015). "Presepsin did not reveal to be useful in predicting bacteremia and it revealed accurate in predicting an unfavorable outcome only 48 h after the onset of fever, being PCT the most accurate biomarker in predicting bacteremia and IL6 the most accurate in predicting an unfavorable outcome." (PMID 37081067, 2023).